NDRG4 (NDRG family member 4)
Diseases named in the same sentence as NDRG4 in open-access papers (continued):
Sharing a sentence is not in itself a finding about the gene and the disease.
breast carcinoma (3 papers, 2019 to 2024). "Taken together, our functional and clinical observations suggest that NDRG4 is a potential mechanistic biomarker in breast cancer that is functionally associated with metastatic disease." (PMID 30963110, 2019). "Of note, NDRG4 expression emerged in this study within a group of epigenetically silenced genes in breast cancer cells that were significantly associated with integrin pathways (e.g., ITGA5 and COL9A3)." (PMID 30963110, 2019). "Taken together, these results suggest that NDRG4 DNA hypermethylation could be used as a complementary prognostic marker for metastatic risk in breast cancer patients." (PMID 30963110, 2019). "NDRG2 has been described mostly as a tumor suppressor, and more information is needed regarding the functions of NDRG3 and NDRG4 in breast cancer." (PMID 38611020, 2024). "An Analysis of samples from breast cancer patients showed that NDRG4 was highly methylated, and patients with methylated NDRG4 had worse overall and distant metastasis-free survival relative to those with non-methylated NDRG4 tumors." (PMID 38611020, 2024). "Taken together, our results suggest that NDRG4 promoter hypermethylation is a promising mechanistic biomarker of metastasis in breast cancer." (PMID 30963110, 2019). "In this study, we provided evidence that NDRG4 is a mechanistic biomarker in breast cancer patients that actively confers distinct metastatic advantages to tumor cells." (PMID 30963110, 2019). "Collectively, these results indicate that NDRG4 controls β1-integrin clustering at the cell-matrix interface and determines the migratory behavior of breast cancer cells towards VN." (PMID 30963110, 2019). "Our results show that NDRG4 knockdown in both breast cancer cell lines significantly increases LN tumor cell adhesion." (PMID 30963110, 2019). "The only study published to date on NDRG4 indicates that NDRG4 may function as a tumor suppressor in breast cancer." (PMID 38611020, 2024). "We next decided to evaluate whether NDRG4 gene silencing has mechanistic relevance during breast cancer progression." (PMID 30963110, 2019). "While NDRG4 downregulation is functionally associated with enhanced lymph node affinity and cell mobility in two non-metastatic and poor invasive breast cancer cell lines, NDRG4 DNA methylation is predictive for the development of metastatic disease." (PMID 30963110, 2019). "Although too speculative at this stage, a possible explanation is that NDRG4 controls β1 integrin recycling in breast cancer cells." (PMID 30963110, 2019). "The NDRG4 gene has been reported to affect the "adhesive switch" by producing epigenetic silencing through promoter hypermethylation, and this gene could be a potential mechanistic biomarker for breast cancer." (PMID 38540412, 2024). "Specifically, we observed NDRG1 amplification in 23% of breast cancer samples, whereas NDRG2 was amplified in 0.9% cases, NDRG3 in 2.5% and NDRG4 in 0.3%." (PMID 38611020, 2024). "NDRG4 has been shown to act via signaling pathways such as cyclin-D1, p27, XIAP, and survivin to increase tumor growth and inhibit apoptosis in other types of cancer, but no information on NDRG4 signaling pathways has been reported in breast cancer." (PMID 38611020, 2024). "To extend these observations to another model, we transfected non-metastatic and poor invasive T47D breast cancer cells with control and specific NDRG4-shRNAs." (PMID 30963110, 2019). "The researchers experimentally silenced NDRG4 expression in two non-metastatic breast cancer cell lines and observed changes in the adhesive and migratory properties of cells that promote tumor invasiveness and spread." (PMID 30963110, 2019).
Cerebral ischemia (3 papers, 2017 to 2025). Restriction of arterial blood supply to the brain associated with insufficient oxygenation to support the metabolic requirements of the tissue. "NDRG4 protein-deficient mice exhibit spatial learning deficits and vulnerabilities to cerebral ischemia." (PMID 29254199, 2017). "NDRG2, NDRG3, and NDRG4 also seem to be involved in brain ischemia." (PMID 31485792, 2019). "After an initial increase of NDRG4, decreased levels of NDRG4 were observed, resembling the expression of NDRG2 and NDRG3 during cerebral ischemia." (PMID 31485792, 2019).
lymph node metastasis (3 papers, 2016 to 2019).
breast tumor (2 papers, 2019 to 2024). "But in breast tumors and in tumor cell lines, methyl tags cover the promoter region of the NDRG4-encoding gene, resulting in reduced protein expression, increased tumor size, elevated cell mobility and other molecular features indicative of a more aggressive disease state." (PMID 30963110, 2019). "Finally, NDRG4 expression was similar in normal and breast tumor tissues and was higher in ER− tumors than in ER+ tumors (p ≤ 0.003)." (PMID 38611020, 2024). "Interestingly, the mechanistic role of NDRG4 in the clustering of β1-integrins in breast tumor cells resembles its role in Nav channel clustering in the Peripheral nervous system (PNS) and CNS." (PMID 30963110, 2019). "Here, we identify N-Myc downstream-regulated gene 4 (NDRG4, also known as SMAP-8 and BDM1) as a novel mechanistic biomarker of metastasis in breast tumors." (PMID 30963110, 2019).
cerebral infarction (2 papers, 2012 to 2025). An ischemic condition of the brain, producing a persistent focal neurological deficit in the area of distribution of the cerebral arteries. "LUT phenotypes for Ndrg4 knockout mice have not been reported but these mutants do exhibit cognitive deficits and they are less tolerant of ischemic stress after cerebral infarction." (PMID 22988430, 2012).
colorectal tumors (2 papers, 2014 to 2017). "Methylation of the SFRP2, GATA4/5, NDRG4 and VIM promoters in fecal DNA is associated with the presence of colorectal tumors." (PMID 25202404, 2014). "We next compared the discriminatory power of these five new markers with two currently acknowledged robust methylation biomarkers for the early detection of colorectal tumors (BMP3 and NDRG4) in the same sample set." (PMID 29371978, 2017).
neuroblastoma (2 papers, 2019 to 2023). Neuroblastoma (NB) is the most common solid, extracranial childhood tumor.
pancreatic cancer (2 papers, 2017 to 2020). "Other stool biomarkers which may be useful in the early detection of pancreatic cancer are NDRG4 or UCHL1." (PMID 33114412, 2020). "Meanwhile, NDRG4 methylation might serve as an early detective biomarker in pancreatic cancer." (PMID 28042954, 2017).
achromatopsia (1 paper, 2018). Achromatopsia (ACHM) is a rare autosomal recessive retinal disorder characterized by color blindness, nystagmus, photophobia, and severely reduced visual acuity due to the absence or impairment of cone function.
autism (1 paper, 2020). Persistent deficits in social interaction and communication and interaction as well as a markedly restricted repertoire of activity and interest as well as repetitive patterns of behavior. "On the one hand, NDRG4 may affect the development of nervous system; on the other hand, it may affect the gastrointestinal function, which is closely related to the occurrence of autism." (PMID 32273901, 2020). "Therefore, NDRG4 may affect the development of nervous system on the one hand and gastrointestinal function on the other hand, which is closely related to the generation of autism." (PMID 32273901, 2020).
Barrett esophagus (1 paper, 2020). Esophageal lesion lined with columnar metaplastic epithelium which is flat or villiform. "We found that NDRG4 was frequent downregulated in esophageal adenocarcinoma through DNA hypermethylation of its promoter region." (PMID 32927604, 2020). "In summary, we have demonstrated that the NDRG4 gene is frequently downregulated in esophageal adenocarcinoma through promoter DNA hypermethylation and may play a tumor suppressor role by inhibiting tumor cell proliferation." (PMID 32927604, 2020). "DNA hypermethylation of NDRG4 may be a useful biomarker in clinical monitoring of esophageal adenocarcinoma patients." (PMID 32927604, 2020). "Interestingly, two cell lines from Barrett’s esophagus demonstrated partial NDRG4 methylation." (PMID 32927604, 2020). "However, the expression pattern of NDRG4 in esophageal adenocarcinoma has not been reported." (PMID 32927604, 2020).
brain glioma (1 paper, 2016). A malignant glioma that involves the brain. "Until recently, investigations found that NDRG4 was overexpressed in human brain glioma and might promote tumor progression, indicating an oncogenetic role of NDRG4, which was opposed to the role of NDRG2 in human brain malignancy." (PMID 26515606, 2016).
cancers of the nervous system (1 paper, 2019). "In the context of nervous system cancers, NDRG1, NDRG2, and NDRG4 have been described to be tumor suppressor genes, although some results are not consistent throughout different studies." (PMID 31485792, 2019).
Chronic colitis (1 paper, 2015). A chronic inflammatory disease of the large intestine (colon, cecum and rectum). "Notably, the positive ratio of NDRG4 in chronic colitis (75.8%) and ulcerative colitis (71.8%) was significantly decreased compared with that in normal mucosa (89.7%), indicating NDRG4 protein expression was associated with inflammation." (PMID 25749388, 2015). "In addition, the positive ratio of NDRG4 in atypical hyperplasia (58.8%) was lower than that in chronic colitis and ulcerative colitis, suggesting NDRG4 was related to early events of carcinogenesis." (PMID 25749388, 2015).
Infertility (1 paper, 2022). "Studies in humans reported a negative feedback loop between NDRG4 activation and consequent PI3-Akt suppression, which could explain the role of NDRG4 in infertility via PI3-Akt suppression." (PMID 36005579, 2022).
intracerebral hemorrhage (1 paper, 2026). A cerebrovascular disorder characterized by bleeding into one or both cerebral hemispheres including the basal ganglia and the cerebral cortex. "NDRG4 expression was significantly reduced in perihematomal brain tissue after intracerebral hemorrhage." (PMID 41484166, 2026).
invasive breast ductal carcinoma (1 paper, 2019). "To further explore previous results in an independent cohort, we examined the correlation between the presence of NDRG4 methylation and well-established prognostic factors in 61 patients with invasive breast ductal carcinoma from AC Camargo Cancer Center (ACC)." (PMID 30963110, 2019).
lung adenocarcinoma (1 paper, 2017). A carcinoma that arises from the lung and is characterized by the presence of malignant glandular epithelial cells. "In the GSE10072 array, expression levels of CDKN2A, PHLDA2, and SFN are significantly upregulated in lung adenocarcinoma compared to normal lung tissue in several datasets, and NDRG4 is downregulated." (PMID 29285217, 2017). "We found that NDRG4 levels were significantly decreased in lung adenocarcinoma, but with regard to survival analysis, the expression of NDRG4 has shown no significant influence on survival rates of lung cancer patients." (PMID 29285217, 2017).
lymph node tumors (1 paper, 2015). "Methylated NDRG4 in metastasis-lymph node tumors from CRC tissues and feces was significantly highly expressed as compared with non-metastatic samples (P<0.05)." (PMID 25663916, 2015).
metastatic disease (1 paper, 2019). "While aberrant NDRG4 DNA hypermethylation is significantly associated with the development of metastatic disease, downregulation of NDRG4 transcription and protein expression is functionally associated with enhanced lymph node adhesion and cell mobility." (PMID 30963110, 2019). "Taken together, our functional and clinical observations imply a causal relationship between NDRG4 status and the aggressive biological behavior of ductal invasive breast cancers, suggesting that NDRG4 is a potential mechanistic biomarker that is functionally associated with metastatic disease." (PMID 30963110, 2019).
myofibromatosis (1 paper, 2017). "A recent exome sequencing study has identified that c.511G>C (p.Val171Leu), a novel NDRG4 homozygous variant, is associated with the autosomal recessive form of infantile myofibromatosis, showing that NDRG4 variations may play an important role in benign tumor." (PMID 28042954, 2017).
Obesity (1 paper, 2016). Accumulation of substantial excess body fat. "In multivariate analysis, among patients with tumor of reduced NDRG4 expression, obesity was found to be independently associated with increased risk of death, with adjusted HR to be 1.67 (95% CI: 1.07–2.60, P = 0.023)." (PMID 26515606, 2016). "Specifically, among patients with tumor of reduce NDRG4 expression, obesity as associated with unfavorable disease-free and overall survival in both univariate and multivariate analysis." (PMID 26515606, 2016). "Then, the association of obesity with clinical outcome was determined according to NDRG4 level." (PMID 26515606, 2016). "The modifying effect of NDRG4 of the prognostic value of obesity indicated that excess energy balance might be detrimental among patients with tumors of NDRG4 reduced expression, probably due to the activation of PI3K/AKT signaling pathway by absence of NDRG4." (PMID 26515606, 2016). "Obesity was found to be adversely associated with disease-free and overall survival in tumors with reduced NDRG4 level, not in preserved NDRG4 level group, in both univariate and multivariate analysis." (PMID 26515606, 2016).
Parkinson disease (1 paper, 2025). A progressive degenerative disorder of the central nervous system characterized by loss of dopamine producing neurons in the substantia nigra and the presence of Lewy bodies in the substantia nigra and locus coeruleus. "Interestingly, NDRG4 was also shown to be differentially methylated and expressed in the substantia nigra, an area of the brain associated with Parkinson’s disease." (PMID 40378957, 2025). "In contrast to the other members of the NDRG family, NDRG4 may be negatively associated with Parkinson’s disease." (PMID 40378957, 2025). "The gene NDRG4 has a lower expression in the cingulate gyrus and substantia nigra of patients with Parkinson’s disease relative to healthy controls." (PMID 40378957, 2025).
pulmonary atresia (1 paper, 2021). "The p.T256M variant in NDRG4 resulted in G1 and G2 arrest of human cardiac myocytes, thereby impairing their proliferative ability, which likely contributes towards the pathogenesis of pulmonary atresia with ventricular septal defect and tetralogy of Fallot." (PMID 33211401, 2021).
tumor (28 papers, 2014 to 2025). "In CRC, loss of N‐Myc downstream‐regulated gene 4 (Ndrg4) function in organoid models triggered neuronal secretion of tumor-promoting factors, including nidogen 1 and fibulin 2, identifying novel therapeutic targets within neurogenic signaling pathways." (PMID 41163091, 2025). "Evidence for functional association between lymph node metastasis and NDRG4 depletion was also observed in vitro, when NDRG4 knockdown contributed significantly to tumor cell adhesion to frozen lymph node sections—a correlate with lymphatic metastasis." (PMID 30963110, 2019). "NDRG4 gene body methylation was found to be significantly associated with age and tumor differentiation." (PMID 28042954, 2017). "The function of NDRG4 in tumor development remains unclear, but numerous studies have indicated that NDRG4 is associated with the growth, differentiation and metastasis of the tumor." (PMID 25663916, 2015). "Briefly, NDRG2 was elucidated to be a tumor suppressor gene in meningioma, while NDRG4 has a proto-oncogenic role in this cancer." (PMID 40378957, 2025). "Chinese scholars identified NDRG4 as a new tumor suppressor gene that plays a tumor suppressive role in SCLC." (PMID 33643409, 2020). "The results further confirmed that reconstitution of NDRG4 suppressed tumor cell growth, as indicated by thinner cell layers in NDRG4 expressing cells as compared to control cells." (PMID 32927604, 2020). "Reconstitution of NDRG4 into tumor cells significantly reduced EdU positive rates in both FLO1 cells (p < 0.001) and OE33 cells (p = 0.006), suggesting a significant inhibition of cell proliferation." (PMID 32927604, 2020). "The colony formation assay confirmed that NDRG4 inhibited tumor cell colony formation capacity in FLO1 cells (p < 0.05) and JH-eso-ad1 cells (p < 0.05)." (PMID 32927604, 2020). "On the other hand, NDRG4 was downregulated in gastrointestinal tract cancers and acted as a potential tumor suppressor." (PMID 32927604, 2020). "To investigate if NDRG4 executes its tumor suppressor function in EAC through inhibiting tumor cell proliferation, we carried out an EdU (5-ethynyl-2′-deoxyuridine) cell proliferation assay in FLO1 and OE33 cell lines." (PMID 32927604, 2020). "In this study, we demonstrated that NDRG4 is expressed in normal breast tissue and is epigenetically silenced by DNA promoter hypermethylation in breast primary tumors and tumor cell lines." (PMID 30963110, 2019). "NDRG4 is downregulated in numerous cancer cell lines and tumor types, and functions as a tumor suppressor gene." (PMID 29254199, 2017). "Both NDRG4 promoter and gene body methylation levels were increased in tumor tissues than paired adjacent normal tissues (P < 0.001)." (PMID 28042954, 2017). "Our findings showed that a much higher hypermethylation rate of NDRG4 gene body in tumor tissues than their adjacent tissues." (PMID 28042954, 2017). "NDRG4 (N-myc down-regulated gene 4) is a tumor suppressor that participates in cell survival, tumor invasion and angiogenesis." (PMID 27175791, 2016). "Results showed that NDRG4 mRNA expression was decreased in tumor specimens and significantly correlated with tumor differentiation, invasion and metastasis." (PMID 26515606, 2016). "NDRG4 is a novel candidate tumor suppressor and can inhibit PI3K/AKT signal which is related with energy balance and related carcinogenesis." (PMID 26515606, 2016). "NDRG4, a new tumor suppressor candidate gene, is located at chromosome 16q21–q22.3, spans 26 kilobases, and contains 17 exons." (PMID 25749388, 2015). "In the present study, the methylated NDRG4 gene expression rates in the tumor and adjacent tissues, were 81 and 8.3%." (PMID 25663916, 2015). "Only demonstrate NDRG4 has the ability to suppress p-AKT can confirm NDRG4 plays its tumor suppressive role in carcinogenesis, progression and prognosis through the suppression of PI3K-AKT activity." (PMID 25749388, 2015).